CFTR (CF transmembrane conductance regulator)
Diseases named in the same sentence as CFTR in open-access papers (continued):
Sharing a sentence is not in itself a finding about the gene and the disease.
infection (continued). "While gene expression of Muc5b and Muc5ac was no different between the two genotypes, at any age, we wondered if the epithelial layer of the CFTR-KO had more mucins in storage, prepared for release into the airway in the event of an infection or in response to an airway irritant." (PMID 35574458, 2022). "Airway epithelial cells, the primary recipients of CFTR gene transfer, play an indispensable role as the first-line host defense in the lung and have a critical role in innate antiviral responses to infection, and thus are resistant to vector transduction or transfection." (PMID 36304167, 2022). "Importantly, excess mucus and mucins have been found in CF lungs prior to detectable infection, strongly suggesting that increased mucin is a direct result of malfunctioning CFTR." (PMID 35574458, 2022). "Additionally, treatment of CF macrophages with CFTR modulators (Teza+Iva) prior to their infection with B. cenocepacia increased the percentage volume of B. cenocepacia colocalized with CFTR, measured by Imaris from z-stack images." (PMID 35252032, 2022). "Additionally, both RNA-seq and RT-qPCR outcomes demonstrated that PON2 and CFTR expression levels were notably increased in response to NDV vaccine infection in thymic tissues of chickens." (PMID 35403571, 2022). "CFTR modulator drugs might therefore affect the development of chronic airway infections and/or improve the status of existing infections in CF." (PMID 35406809, 2022). "Even in the absence of infection, loss of CFTR alone contributes to significant dysregulation of nearly every cytokine involved in cell mediated and adaptive immunity." (PMID 34475490, 2021). "These factors could make infection eradication challenging even if CFTR-dependent host defenses were normalized." (PMID 34903059, 2021). "On the one hand neutrophils are recruited to inflamed CF airways, even in the absence of infection, due to continuous NF-κB signaling and pro-inflammatory cytokine secretion, however, neutrophils also show a primary defect linked to CFTR dysfunction." (PMID 33986686, 2021). "Similarly, aberrant CFTR expression and thus CFTR function reduce the ability of myeloid cells to successfully resolve infection and inflammation." (PMID 34054511, 2021). "Recent studies showed that infection with pathogens including Campylobacter jejuni and Toxoplasma gondii impaired the function of epithelial Cl− secretion mediated by CFTR, suggesting a close correlation between pathogen infection and aberrant function of CFTR in host epithelial cells." (PMID 33861752, 2021). "In addition to its classical role in ion transport, CFTR is known to mediate bacterial phagocytosis and regulate innate immune responses, where its genetic or acquired dysfunction promotes recurring infections and chronic exacerbations." (PMID 33546140, 2021). "We’ve found significant differences between non-CF and CF mice in the absence of detectable infection, implying these differences are primarily attributable to the loss of CFTR." (PMID 34475490, 2021). "Our finding that infection clearance may be associated with low sweat chloride raises the possibility that infection clearance rates might be increased if CFTR function could be improved further." (PMID 34903059, 2021). "Owing to this widespread distribution of the CFTR protein, CF is a multisystem disease, although lung involvement, characterized by bronchial obstruction, infection, and inflammation leading to bronchiectasis and progressive pulmonary injury, remains the main cause of morbidity and mortality." (PMID 34831067, 2021). "The CF microenvironment resulted from a CFTR malfunction may have an unwanted effect in contributing to the infection and colonization of P. aeruginosa." (PMID 34867864, 2021).
infection (continued). "While chronic bacterial infection has long been recognized as the main stimulus for airway inflammation in CF, increasing evidence suggests that the inflammatory response in CF lungs occurs early in the disease course, before any infection, and supports the crucial role of the CFTR protein." (PMID 34831067, 2021). "Cytokine production was unchanged or decreased in response to infection in CFTR KO MDMs." (PMID 32973772, 2020). "Using a vector carrying fragments of the cystic fibrosis transmembrane conductance (CFTR) locus, infection of 2 × 106 human induced pluripotent stem cells (iPSC) at MOI 350 obtained up to 144 clones harboring integration of the template DNA after positive selection." (PMID 32455640, 2020). "In this model, we could show high basal levels of NF-κB activation after CFTR inhibition, which further increased following infection with MDR P. aeruginosa." (PMID 33117337, 2020). "Moreover, we have harnessed the CFTR zebrafish model of infection as an innovative vertebrate recapitulating aspects of CF immuno-pathogenesis." (PMID 32850470, 2020). "Therefore, autophagy and CFTR share an intimate relationship in terms of regulating the immune response against infections." (PMID 32847034, 2020). "It has been discussed, that CFTR genotype might correlate with infection and pathogenicity of certain pathogens, and interfere with CFTR modulator treatment." (PMID 33149181, 2020). "Upon infection with BKPyV, we also observed a ~25% (p ≤ 0.0003) increase in the levels of CFTR mRNA expression, suggesting that the virus may up-regulate CFTR expression." (PMID 32229236, 2020). "There is an ongoing debate as to whether correcting the primary ion transport defect, with CFTR modulators alone, can resolve both infection and inflammation, two key components driving CF lung pathology." (PMID 32118580, 2020). "Infection of ORKAMBI®-rescued F508del-CFTR cells with clinical strains of P. aeruginosa that were isolated from the sputum of CF patients showed a range in loss of CFTR function, with one strain reducing CFTR activity by as much as 88% (strain PA330)." (PMID 32092967, 2020). "Besides infection, CFTR-autophagy dysfunction can lead to an impaired clearance of cellular debris and products that would normally be degraded." (PMID 32847034, 2020). "Here, we show that the infection of F508del-CFTR human bronchial epithelial (HBE) cells with lab strain and four different clinical strains of P. aeruginosa, isolated from the lung sputum of CF patients, decreases CFTR function in a strain-specific manner by 48 to 88%." (PMID 32092967, 2020). "The presence of the corrector VX-809 did not lower bacterial load on PAO1 infected F508del-CFTR cells and did not improve the loss of F508del-CFTR function in the infection model." (PMID 32092967, 2020). "We describe the aggressive and lethal infections caused by M. fortuitum, which develops in the absence of either functional innate immunity or CFTR." (PMID 32850470, 2020). "Infection with clinical strains decreased F508del-CFTR function by 48–88%, dependent on the strain." (PMID 32092967, 2020). "Whether CFTR/DUOX2 NADPH axis differentially regulates sterile or infection-induced neutrophilic inflammation remains to be addressed." (PMID 32849617, 2020). "Mabs infection triggers an upregulation of nox2 in control fish and qRT-PCR analysis confirmed a reduced nox2 expression in cftr morphants, suggesting that CFTR orchestrates the early regulation of ROS induction by modulating the NOX2/NADPH oxidase activity." (PMID 30759393, 2019). "Thus, new animal models that approximate the human altered immune phenotype and allow direct visualization of host-pathogen interactions would provide much needed tools to establish in vivo how CFTR regulates innate immunity and controls Mabs infection." (PMID 30759393, 2019).
infection (continued). "Thus, intracellular ROS generation in CFTR-deleted larvae was investigated as a plausible mechanism through which CFTR-mediated oxidative stress controls Mabs infections." (PMID 30759393, 2019). "Therefore, lack/dysfunction of CFTR eventually leads to dehydration of airway secretions, ablation of the mucociliary clearance, and airway colonisation and infection by opportunistic bacterial pathogens, including the gram-negative Pseudomonas aeruginosa." (PMID 29531530, 2018). "Nevertheless, it should be noted that, in line with the present findings, a similar stimulatory trend was reported in previous studies using infection with short hairpin RNA interference-expressing lentiviruses, which suppressed the CFTR protein expression by 50%." (PMID 29954133, 2018). "To understand if treatment with CFTR modulators could alter CF macrophage responses to infection, we sought to characterize macrophage responses to clinical treatment with CFTR modulators." (PMID 30459435, 2018). "Moreover, it is also important to note that both Pa-infection and neutrophil elastase can negatively affect CFTR expression and/or function." (PMID 29301535, 2018). "As CF lung pathology is characterised by chronic inflammation and infections, future work should assess whether hAMSCs are useful in this context, besides the rescue of a mature and functional CFTR protein." (PMID 29531530, 2018). "Overproduction of the neutrophil chemokine IL-8 by CF airway epithelial cells may be a consequence of both intrinsic CFTR dysfunction and infection." (PMID 29849481, 2018). "Since these samples had been stored for an extensive time, we also analyzed BAL samples from CFTR knockout rats and their littermates under baseline conditions and after infection with 3 × 10^6 CFU of a clinical mucoid Pseudomonas (PAM57-15) by intratracheal instillation." (PMID 29085059, 2017). "CFTR having a role in innate host response to infection was a postulated explanation." (PMID 27927212, 2016). "Hence, in SHS induced infections, P. aeruginosa is expected to inhibit its phagocytosis by depleting CFTR dependent rafts." (PMID 25794013, 2015). "Although links have been established between epithelial CFTR dysfunction, defective bacteria clearance, and intense inflammatory responses, the relationship between CF airway inflammation and infection remains unclear." (PMID 26485688, 2015). "Similarly, incubation with the CFTR corrector and/or the CFTR potentiator also decreased IL-8 expression in response to infection." (PMID 26793709, 2015). "Additionally, CFTR–/– mice infected with CHB756 and CHB1126 were more susceptible to infection than WT-mice (P≤0." (PMID 26469863, 2015). "This may explain why CFTR−/− mice are more vulnerable to muscle wasting and produce more myokines upon an infection with P. aeruginosa compared to CFTR+/+ mice." (PMID 23497303, 2013). "They postulated that under normal situations, CFTR is a receptor for LPS and induces the internalisation of P. aeruginosa, the induction of the inflammatory response, apoptosis and, during infection with P. aeruginosa, the presence of CFTR increases in microdomains." (PMID 21490807, 2011). "Similar to what was observed for scAAV2, 24 hr after inoculation of single-stranded rAAV2, the expression of GFP or Luc reporters indicated that infection was significantly more efficient in ΔF508-CFTR-expressing cells than in control or CFTR-overexpressing BHK-21 cells." (PMID 21625534, 2011). "For those with decreased lung function, 'Residual' CFTR genotype no longer provides a protective effect on infection risk." (PMID 20932301, 2010). "Infection of Caco-2/15 cells with lentivirus carrying CFTR-shRNAi caused a reduction in CFTR gene (61%) and protein (57%) expression when compared to non-infected cells." (PMID 20463919, 2010). "Therefore, in order to fully benefit from CFTR-targeting medicines, infection control measures could be necessary." (PMID 40804904, 2025).
infection (continued). "Additionally, in people with CF for whom CFTR modulator treatments have been appropriate, improvements in lung function have been seen, but they have not improved underlying infection rates." (PMID 39861758, 2025). "The defective CFTR function results in the formation of a viscous mucous layer that, on the one hand, impairs mucociliary clearance thus favoring microbial persistence and pathogen infection, and, on the other hand, damages epithelial cells and promotes a pathogenic inflammation." (PMID 38721278, 2024). "In addition, management of persistent inflammation and infection requires anti-inflammatory and anti-infective therapies that may support CFTR modulator therapy." (PMID 38607074, 2024). "By contrast, mutational loss of CFTR, either in cultured CF lung epithelial cells or in differentiated lung epithelia from CF patients, were associated with mislocalization of ACE2 away from the apical plasma membrane, thereby compromising infection by SARS-CoV-239." (PMID 39043712, 2024). "We believe that research on this topic is timely and warranted since a majority of pwCF currently take CFTR modulators, live longer, and maintain persistent microbial colonisations with recurrent infections that may change the microbial landscape of the CF lung." (PMID 39595943, 2024). "For example, newborn CFTR−/− pigs display early congenital airway abnormalities, including lowering of pH which hinders the bacteria killing function of airway surface liquid, defects in mucus detachment from submucosal glands, and early infection that precedes inflammation and remodeling." (PMID 39439894, 2024). "However, many results suggest that CFTR dysfunction causes a dysregulated inflammatory response, which is partly due to defective expression of CFTR in immune cells, and that CF airways are already a perfect microenvironment for amplifying the immune–inflammatory mechanisms before any infection." (PMID 37371820, 2023). "However, specific decreases in function of either CaCC in the cecum and CFTR in the distal colon may suggest the involvement of more physiological mechanisms of regulation during infection." (PMID 37350393, 2023). "Therefore, our results demonstrate that CFTR dysfunction in epithelial cells is sufficient to cause an oxidative status imbalance in the airway epithelium, independent of immune cells and infection." (PMID 37619220, 2023). "Moreover, OLE is an effective and economic natural herb that seems to improve the efficacy of CFTR modulators therapies under infection stimuli, which could provide a clear benefit to CF patients with P. aeruginosa colonization." (PMID 37443798, 2023). "Altogether, these results showed that organoids derived from CF lung tissue exhibited not only CFTR dysfunction and exacerbated mucus accumulation but also an increased oxidative stress, therefore representing a suitable ex vivo model to investigate how the lung CF context drives Mabs infection." (PMID 37619220, 2023). "CFTR modulators function by improving the activity of ion channels, therefore, it is feared that they may also improve function of bacterial ion channels, increasing the removal of antimicrobials contributing to infection." (PMID 35408875, 2022). "Furthermore, it remains unknown whether the restorative effects exerted by CFTR modulators extend to immune cells, such as phagocytes, which have the potential to modulate the response of people with CF (pwCF) to infection." (PMID 35408875, 2022). "Indeed, much of the lung damage that occurs in CF results from the deleterious effects of an overexuberant inflammatory response to infection, as the host is incapable of controlling microbial growth due to intrinsic host defense defects related to CFTR dysfunction." (PMID 36480571, 2022).
infection (continued). "In addition, restoring junctional complexes in the CFTR-KD cells by the addition of an apical liquid volume is sufficient to preserve the epithelium integrity during infection with PAO1 mutant strains, a protection that was maintained even when ASL was removed prior to infection." (PMID 35563895, 2022). "Treatment of CF remains complex, and recent advances in therapeutics such as CFTR correctors and modulators have helped not only to improve patients’ life expectancy but also to enhance our understanding of other aspects of the disease, like infection and inflammation." (PMID 36553341, 2022). "Moreover, HDAC6 inhibitors could also flank CFTR-targetedtherapies in order to improve the management of inflammation, fibrosisand infection in CF." (PMID 35148101, 2022). "However, it remains unclear whether this dysfunction arises from a primary intrinsic abnormality in the immune cells or if the dysfunction is a byproduct of the infection microenvironment created by the CFTR defect." (PMID 35315363, 2022). "The absence of CFTR-mediated chloride and bicarbonate secretion has been functionally linked to airway surface dehydration, which leads to the accumulation of thick mucus, increased susceptibility to infection and inflammation." (PMID 36430961, 2022). "Absence of CFTR-mediated Cl-secretion has been functionally linked to airway surface dehydration, which leads to the accumulation of concentrated mucus, airway obstruction, inflammation and infection, bronchiectasis, and ultimately death." (PMID 34830048, 2021). "Thus, defective CFTR expression and function appears to be driving inflammation, by lowering the threshold of innate immune defences and reducing the ability of myeloid cells, such as neutrophils and macrophages to resolve infection and inflammation." (PMID 32118580, 2020). "Moreover, chronic treatment with 128 μg/mL 6K-F17 (c128) for 24 h prior to infection results in the complete inhibition of bacterial growth and restoration of F508del-CFTR function, which indicates that the peptide is stable on HBE cells over 24 h and it has the potential for preventive care." (PMID 32092967, 2020). "The prospect that multiple key CF phenotypes can be addressed by HDAC6 inhibition is important for patients with CFTR mutations not currently responsive to potentiator and corrector therapies, or to even augment CFTR-targeted therapies to improve inflammation and infection management." (PMID 31311988, 2019). "Additionally, the effects of the CFTR genotype on apoptosis of lung epithelial cells at baseline or after Pa infection are still debated and may be dependent on which specific marker of apoptosis is being evaluated." (PMID 30555487, 2018). "However, tackling lung function impairment in CF patients has remained a challenge, and continuing effectors towards either restoring host function (CFTR function and mucociliary clearance) or controlling disease progression (inflammation and infection) are required." (PMID 27919253, 2016). "Our findings suggest that defects in CFTR may increase susceptibility of mice to lung infections with the highly mucoid serotype 3 Sp despite similar lung histopathology and levels of TNF- α and CXCL1/KC produced early in infection." (PMID 26469863, 2015). "Lack of CFTR in transgenic CF mice has similarly been shown to lead to increased levels of Pa in the lung which are associated with hypersusceptibility of CF mice to mucoid Pa infection." (PMID 26469863, 2015). "It is not clear whether the decreased activity of the enzyme is associated with the lack of expression of CFTR gene or is formed secondary to infection and inflammation." (PMID 24803981, 2014). "Recent success in the identification of small molecules augmenting CFTR function raises the possibility that delay of infection might be used as a measure for clinical efficacy of these new treatments, especially in children where few alternative options exist." (PMID 20932301, 2010).